GPC1 (glypican 1)
Diseases named in the same sentence as GPC1 in open-access papers (continued):
Sharing a sentence is not in itself a finding about the gene and the disease.
pancreatic cancer (continued). "Levels of glypican 1 (GPC1)-circulating exosomes help to distinguish between healthy subjects and patients with benign pancreatic disease from patients with early- and late-stage pancreatic cancer." (PMID 36675253, 2023). "Furthermore, migration inhibitory factor (MIF) was reported to have better performance than GPC-1 and EGFR in the discrimination of different stages of pancreatic cancer." (PMID 35180868, 2022). "In addition, downregulation of GPC-1 attenuated TGF-β1 signaling and Smad2 phosphorylation to suppress pancreatic cancer cell growth." (PMID 36313694, 2022). "HPSC exosomes were enriched with the proteoglycan, glypican-1 (GPC1), which was suggested as a biomarker to detect PDAC; however, another study reported that exosomal GPC1 was unable to differentiate patients with pancreatic cancers from healthy controls." (PMID 36332889, 2022). "Although GPC-1 was found to be indicative, it has been revealed that GPC-1 alone is not convincing for the diagnosis of pancreatic cancer." (PMID 36167539, 2022). "Indeed, two pancreatic cancer cell lines (COLO-357 and PANC-1) were treated with phosphoinositide-specific phospolipase-C (PI-PLC), an enzyme responsible for the release of GPC1 from the cell membrane by GPI-anchor cleaving." (PMID 36142190, 2022). "With circulating levels of Glypican-1 (GPC1) as a specific proteoglycan on cancer exosome surface healthy individuals, patients with benign pancreatic and different stages of pancreatic cancer could be adequately distinguished." (PMID 35008381, 2022). "Glypican-1 (GPC-1), a surface-bound proteoglycan that regulates signaling pathways mediated by TGF-β, Wnt, and other growth factors, is overexpressed in a variety of cancer tissues to promote cancer progression, especially pancreatic cancer." (PMID 35757760, 2022). "In pancreatic cancer patients, glypican-1 (GPC-1), a membrane-anchored proteoglycan, and GPC-1+ exosomes were found with a higher level in serum than in healthy people, and they had great sensitivity and specificity in the diagnosis of early pancreatic cancer." (PMID 33922480, 2021). "Indeed, the proteoglycan glypican-1 (GPC1) and the tumor antigen chondroitin sulfate proteoglycan 4 (CSPG4) were detected in tumor exosomes from heterogeneous samples of pancreatic cancer or melanoma, respectively." (PMID 33430152, 2021). "GPC1 is a GPI-anchored heparan sulfate proteoglycan that is overexpressed in several cancers, including pancreatic cancer and CRC, and exosomal GPC1 in the plasma is reported to be a sensitive and specific biomarker for the early detection of pancreatic cancer." (PMID 34887515, 2021). "Other researchers observed that GPC1 is also elevated in exosomes of pancreatic cysts, and in other tumors, such as colon cancer, and is therefore not strictly specific to pancreatic tumors." (PMID 34249755, 2021). "The upregulation of GPC1 and GPC4 is found in pancreatic cancer." (PMID 32916872, 2020). "Hence, enumeration of GPC1-positive EVs, solely or in conjunction with GP2, was unable to effectively distinguish between BPD and pancreatic cancer." (PMID 30800217, 2019). "Overall, the findings of this study led us to conclude that since GPC1 cannot discern late-stage, metastatic pancreatic cancer from benign pancreatic diseases, GPC1 is not useful in the early detection of pancreatic cancer." (PMID 30800217, 2019). "Reduced GPC-1 expression attenuated the TGF-β1 induced inhibition of cell growth, with suppressed Smad2 phosphorylation, and plasminogen activator inhibitor-1(PAI-1) promoter activity in pancreatic cancer cells." (PMID 31355137, 2019). "However, it has been found that glypican-1 (GPC1), a cell surface proteoglycan, specifically enriched on pancreatic cancer-cell-derived exosomes, is of significance for the diagnosis of early pancreatic cancer." (PMID 30148165, 2018).
pancreatic cancer (continued). "Intriguingly, glypican-1 (GPC1), a cell-surface proteoglycan, was specifically enriched on cancer-cell-derived exosomes and this was correlated with tumor burden and the survival of patients with pancreatic cancer." (PMID 30400814, 2018). "The overall survival and disease-free survival were not correlated with GPC1 expression in pancreatic cancer cells or in pancreatic cancerous stromal cells in our clinical cohorts." (PMID 29245923, 2017). "In the human pancreatic cancer cell line, PANC-1 cells, downregulation of GPC1 using antisense RNA resulted in slower growth and decreased anchorage-independent growth in vitro as well as attenuated tumor growth, angiogenesis, and metastasis in vivo when these cells were transplanted into mice." (PMID 29230082, 2017). "An earlier report described that GPC1 overexpression is correlated with poor prognosis in pancreatic cancer, but our results did not indicate differences in prognoses between GPC1-positive cases and GPC1-negative cases." (PMID 29245923, 2017). "It has also been recently identified that a cell surface proteoglycan, glypican-1 (GPC1), is specifically enriched in pancreatic cancer-cell-derived EV, showing that EV may also have potential as cancer biomarkers." (PMID 28881726, 2017). "No direct correlation of GPC1 expression was found between pancreatic cancer cells and pancreatic cancer stroma." (PMID 29245923, 2017). "GPC1 was not expressed in intestinal-type pancreatic neoplasms, which tend to occur in main pancreatic duct and which have the potential to transform to invasive carcinoma." (PMID 29245923, 2017). "Furthermore, inhibition of GPC1 and/or EVI1 is an important therapeutic target in pancreatic cancer." (PMID 29245923, 2017). "The lack of clear correlation of GPC1 expression levels with pancreatic cancer prognosis is also in line with this notion." (PMID 29245923, 2017). "GPC1 is involved in tumor growth and angiogenesis through the activation of FGF-FGFR signaling and GPC1 expression can be suppressed by miR-96-5p in pancreatic cancer cells or regulated by miRNA-149 in human endothelial cells." (PMID 29254156, 2017). "The same is true when cell line-derived exosomes were analyzed using GPC1 immunoaffinity isolation (data not shown), suggesting that GPC1 positive exosomes do not provide an advantage for detection of localized pancreatic cancer in plasma exosome miRNA." (PMID 29100367, 2017). "A high expression level of GPC1 mRNA was detected in a pancreatic cancer cell line (AsPC-1) compared to a non-cancerous cell line (HPDE6-C7) by qRT-PCR." (PMID 29162835, 2017). "Their results suggest that GPC1 + circulating EVs could be a potential biomarker for noninvasive diagnosis and screening for pancreatic cancer." (PMID 37798669, 2023). "Similarly, treatment with mAbs targeting podocalyxin, HER2, glypican-1, cell surface plectin 1, galectin-9, RON, BAG3, CLDN18.2, mesothelin, vimentin and doublecortin-like kinase 1 inhibited the growth of pancreatic tumours in xenograft models." (PMID 33917882, 2021). "An earlier study suggested that levels of glypican 1 expressing EVs could discriminate between early- and late-stage pancreatic cancer, benign pancreatic disease and non-cancer controls." (PMID 34571828, 2021). "Exosomes express glypicans on their cellular surface and recently glypican 1+ (GPC1) exosomes have been identified for the detection of pancreatic cancer independent of staging in multiple studies, emphasizing the great potential of exosome-based biomarkers for gastrointestinal cancers." (PMID 31100935, 2019). "The rarity of GPC1-positive EVs and lack of consistent co-occurrence with GP2 in pancreatic cancer patients challenge the notion that GPC1 present on EVs is exclusively found and derived from cancer of the pancreas (given that patients are unaffected by other cancers)." (PMID 30800217, 2019).
pancreatic cancer (continued). "However, Lai and colleagues reported that exosomal GPC1 is not able to distinguish pancreatic cancers from non-tumorous controls and that the levels of exosomal GPC1 were only slightly lower after resection." (PMID 29282096, 2017). "In a clinical cohort, GPC1 overexpression was not correlated with pancreatic cancer prognosis." (PMID 29245923, 2017). "Thus, we select GPC1 mRNA as a model biomarker, which supposes to be enriched in pancreatic cancer cell-secreted EVs rather than EVs secreted from normal cells, to verify our novel assay." (PMID 29162835, 2017). "Furthermore, no explanation exists for some cases in which a drop of GPC1 value was insufficient after surgical resection of pancreatic cancer." (PMID 29245923, 2017). "Glypican-1 (GPC1) which was demonstrated specifically enriched on cancer cell-derived exosomes and showed great specificity over CA-199 or serum-free GPC1 (100% vs 79.49% vs 82.14%) in distinguishing non-cancer subjects from pancreas cancer patients." (PMID 29282096, 2017). "Considering that GPC1 was expressed from precancerous lesions of the pancreas, GPC1 might not be involved in the malignant potential of the advanced phase of pancreatic cancer." (PMID 29245923, 2017). "From in vitro assays, we found that GPC1 committed to cellular proliferation or migration, that EVI1, KRAS and/or miR-96 regulated expression of GPC1, and that EVI1 modulated the oncogenic role of GPC1 in both pancreatic noncancerous cell lines and pancreatic cancer cell lines." (PMID 29245923, 2017). "Beside its prognostic role in pancreatic cancer, there is currently no other indication that altered expression of GPC1 may influence the course of any tumour type." (PMID 25935541, 2015). "Moreover, when comparing to ORI and ORI-NPs, NCs targeting GPC1 dramatically decreased the viability and increased apoptosis of BXPC-3 and PANC-1 (pancreatic cancer cell lines overexpressing GPC1) but not 293 T cells (pancreatic cancer cell line negative for GPC1)." (PMID 37981671, 2023). "Therefore, further investigation of GPC1 expression in different CAF subtypes is warranted as well as whether our GPC1-specific CAR T cells could re-model the tumor microenvironment and destroy GPC1-positive pancreatic cancer cells." (PMID 37031249, 2023). "A gating of only EVs between 110-150nm meant to enumerate GPC1+ve, GP2+ve or GPC2 and GP2 dual positive exosomes (small EVs) also failed to distinguish between patients with BPD and pancreatic cancer." (PMID 30800217, 2019). "Overall, the presence of GPC1 fails to distinguish between patients with BPD and pancreatic cancer." (PMID 30800217, 2019). "Whether through the analysis of GPC1 alone or in conjunction with GP2, target EV counts between all three groups did not significantly differ and thus was not informative regarding pancreatic cancer status." (PMID 30800217, 2019). "Moreover, mice that lacked GPC1 exhibited decreased tumor angiogenesis and metastasis following intrapancreatic implantation with either PANC-1 or T3M4 human pancreatic cancer cells and had fewer pulmonary metastases following intravenous injection of murine B16-F10 melanoma cells." (PMID 29230082, 2017).
breast carcinoma (56 papers, 2004 to 2025). "α3(V) and GPC1 expression levels are tightly associated in human breast cancer types, consistent with possible functionally meaningful interactions, with distributions of expression levels of both proteins in the order luminal A>>luminal B>>basal-like." (PMID 28102194, 2017). "However, if we look at breast cancer stratified by receptor status, we find that in ER-negative breast cancer, low expression of GPC1 is associated with longer RFS in patients." (PMID 33742285, 2021). "Interestingly, GPC1 knockdown resulted in markedly reduced α3(V) levels in mammary tumour cell-associated ECM." (PMID 28102194, 2017). "Interestingly, high expression levels for both the α3(V) gene COL5A3 and the GPC1 gene are strongly associated with luminal A breast tumours, with expression level distribution of both genes in human breast cancer in the order luminal A>>luminal B>>basal-like (P<0.0001)." (PMID 28102194, 2017). "GPC1 expression was increased in hepatocellular carcinoma, breast cancer, cervical cancer, prostate cancer, and glioma." (PMID 39300946, 2024). "In a recent study, a droplet digital ExoELISA method was developed for the detection of GPC-1(+) exosomes in clinical samples from healthy individuals, patients with benign breast cancer, patients with breast cancer, and post-breast cancer patients." (PMID 39617822, 2024). "For example, a magnetic bead pellet coupled with a CD63 antibody was utilized to capture target sEVs (Glypican-1 (GPC-1)) from the plasma of early-stage breast cancer patients." (PMID 39639411, 2024). "Stable transfection of MDA-MB-231 and MDA-MB-468 breast cancer cells with a GPC1 antisense construct markedly decreased GPC1 protein levels and the mitogenic response to heparin-binding (HB)-EGF, FGF2, heregulin α, heregulin β, and HGF." (PMID 38966167, 2024). "Considering their cellular membrane location, it is not surprising that glypican proteins are a component of the secretory pathway as GPC-1 has been observed in pancreatic and breast cancers." (PMID 37446098, 2023). "As a cell surface heparan sulfate proteoglycan, GPC1 was found to exhibit a mitogenic response to multiple heparin-binding growth factors and lead to progression in breast cancer." (PMID 37534104, 2023). "We also observed increased levels of Col4A5 and glypican (GPC) GPC1 in lung fibroblasts exposed to conditioned media from both breast cancer cells, which approached statistical significance." (PMID 37903851, 2023). "Glypican-1 (GPC-1) is a cell surface proteoglycan that is upregulated in some types of human cancers, such as breast cancer (BC), esophageal squamous cell cancer (ESCC), and PC." (PMID 36313694, 2022). "Our study has shown that in unclassified breast cancer, high GPC1 levels lead to a longer RFS compared to those with lower levels." (PMID 33742285, 2021). "GPC1 has received growing interest in recent years due to its high capability of visualizing soft tissue, and GPC1 has been reported to have potential value in the diagnosis of breast cancer." (PMID 35223866, 2021). "To approach this research question, firstly we utilized a large cohort of breast cancer patients to analyze the impact GPC1 to GPC6 have on their relapse-free survival." (PMID 33742285, 2021). "The qualities of GPC1 as a potential novel biomarker for prognosis of breast cancer, especially triple-negative breast cancer, were also suggested in a recent study on exosomal proteomes." (PMID 33742285, 2021). "In breast cancer, GPC1 is overexpressed and modulates heparin-binding growth factors and FGF2, thus suggesting a role in breast cancer progression." (PMID 33742285, 2021). "GPC1 is a membrane-anchored protein that has diverse functions and it is overexpressed in several types of tumors including glioma, breast cancer, and PC." (PMID 33297544, 2020). "GPC-1 expression was also increased in breast cancer tissues, ovarian malignant tumors, prostate cancerous epithelial cells." (PMID 31355137, 2019).
breast carcinoma (continued). "Similar to breast cancer, GPC1 also has been shown to have growth-promoting effects in pancreatic cancer and gliomas." (PMID 30197623, 2018). "Breast cancer cells are also shown to overexpress HSPGs, such as Glypican 1 (GPC1) and Syndecan 1 (SDC1), which enhance the proliferative response after treatment with various growth factors due to prolonged signaling." (PMID 30197623, 2018). "α3(V) chains are produced in both basal-like and luminal human breast tumours, and its expression levels are tightly coupled with those of glypican-1 across breast cancer types." (PMID 28102194, 2017). "That α3(V)-GPC1 interactions are functionally important is supported by the observations that α3(V) ablation results in reduced mammary tumour cell proliferation, Ras/Erk signalling, and cell cycle progression—just those properties stimulated by GPC1." (PMID 28102194, 2017). "Of these, glycoprotein glypican – 1 (GPC1), which, although found circulating at low levels in healthy patients sera, was higher in patients with breast cancer (n = 32, 75%) and pancreatic ductal adenocarcinoma (PDAC, n = 190, 100%)." (PMID 28936255, 2016). "On the contrary, in the same study GPC1 was found to be strongly expressed in human breast cancers with a low expression in normal breast tissues." (PMID 25140302, 2014). "For example, syndecan-2 and syndecan-4, as well as glypican-1, are overexpressed in breast cancer cell lines, compared to normal mammary cells, and are mediators of growth factor signaling." (PMID 23984412, 2013). "Furthermore, high expression of GPC-1-Exo has been observed in breast cancer tissues and cells relative to normal breast tissues." (PMID 38720811, 2024). "Importantly, COL5A3 has been reported to enhance proliferative potential in breast cancer cells via binding a membrane proteoglycan GPC-1." (PMID 36712590, 2023). "Huang’s study showed that GPC-1 promotes tumor cell mitosis by modulating FGF2 in breast cancer." (PMID 36313694, 2022). "The HSPGs GPC1 and SDC1, overexpressed in a high percentage of breast cancer pathologies, enhance the mitogen effects associated with heparin-binding growth factors like Basic Fibroblast Growth Factor (FGF2), HBEGF and Hepatocyte growth factor (HGF), promoting cell proliferation." (PMID 33494442, 2021). "In addition, GPC1 modulates heparin-binding growth factors and plays a role in tumour progression in breast cancer." (PMID 33494442, 2021). "In breast cancer patients, 75% had higher GPC-1+ exosomes than the healthy controls." (PMID 31355137, 2019). "Quantification of GPC-1 level is also pivotal to breast cancer and prostate cancer’s patients." (PMID 30202003, 2018). "Recently, a study of patients with breast cancer detected glypican-1- and CD24-positive exosomes in patient serum samples, which may be used as biomarkers of breast cancer." (PMID 28659795, 2017). "GPC1 has been discovered to have a higher expression in breast cancer tissues and cells than normal breast tissues and may contribute to the progression of breast cancer." (PMID 35265226, 2022). "Moreover, compared with levels in breast cancer patients, GPC1+ crExos was higher in PDAC patients." (PMID 28440066, 2017). "We prepared magnetic beads conjugated with antibodies targeting specific breast cancer markers found in EVs, including epithelial cell adhesion molecules (EpCAM or CD326), CD49f, CD51, CD49b, and glypican-1 (GPC-1)." (PMID 39479442, 2024). "Among them, three exosomal membrane/surface proteins, glucose transporter 1 (GLUT-1), glypican 1 (GPC-1), disintegrin, and metalloproteinase domain-containing protein 10 (ADAM10), were identified as potential breast cancer biomarkers." (PMID 37893211, 2023). "For example, glypican-1 in circulating exosomes demonstrated discrimination between PDAC patients and healthy controls with 100% sensitivity and specificity; however, breast cancer patients also display high values indicating insufficient PDAC specificity." (PMID 36361759, 2022).